BCL2 (BCL2 apoptosis regulator)
Diseases named in the same sentence as BCL2 in open-access papers (continued):
Sharing a sentence is not in itself a finding about the gene and the disease.
tumor (continued). "Bcl-2 is recognized as a novel type of multidrug-resistant protein that protects tumor cells from the cytotoxic effects of virtually every anticancer drug currently available." (PMID 24711740, 2014). "Beside its anti-apoptotic effects, PTX has been shown to induce apoptosis in certain conditions, e.g. by increasing bax expression in a greater extent than bcl2 in tumour cells." (PMID 24523936, 2014). "To determine the expression of Bax, Bcl-2, p21, and Ki67 in tumor tissues, we conducted IHC staining in tumors with over-expressed CAM2KN1." (PMID 25003983, 2014). "In order to evaluate the impact of S44563 on the expression of Bcl-2, Bcl-XL, and Mcl-1 proteins, two to four tumor samples have been collected at the time of mice sacrifice for immunohistochemical studies." (PMID 24454684, 2014). "The significantly higher percentage of tumours overexpressing BCL-2 was also found in LA and LB than in HER2+ and TN cancer immunophenotypes, identified on the basis of ER, PgR, HER2 and Ki-67 expression according to St." (PMID 25005788, 2014). "BCL-2 overexpression was significantly related to lower tumour grades (P = 0.001), positive hormonal receptors status (P = 0.000) and CK5/6 negativity (P = 0.015)." (PMID 25005788, 2014). "This relationship was not altered after individual adjustment by patient-related (age, race, or BMI) or tumor-related (HR, Ki67, grade, or Bcl2) variables." (PMID 24719175, 2014). "Since then, high BCL2 expression has been reported in many different tumour types including lung cancer, ovary cancer, and breast cancer." (PMID 26556430, 2014). "Most primary tumor masses before treatment showed Bcl-2 expression in at least 25% of cells, but Bax expression in less than 10% of tumor cells." (PMID 24479409, 2014). "This miRNA functions as a tumor suppressor by inhibiting the expression of B-cell lymphoma-2 (BCL2), and plays an important role in controlling B cell homeostasis." (PMID 24637658, 2014). "Results were very encouraging with decreased Bcl-2 expression, increased apoptosis and reduction of tumor growth seen in those treated with oblimersen in comparison to control oligonucleotides or cisplatin." (PMID 24840048, 2014). "A potential mechanism is intrinsic, and possibly acquired, tumor cell resistance to therapy-induced cell death (apoptosis) by dysregulation and release of anti-apoptotic inhibitor of apoptosis protein or Bcl-2 proteins." (PMID 26056594, 2014). "Previous studies have shown that Gos downregulated the expression of Bcl-2/Bcl-XL/Mcl-1 proteins in multiple tumor cell lines." (PMID 25231749, 2014). "All patients (n = 18) characterized by tumour BCL-2 positivity, low TOPOIIα expression and high MVD survived 80 months without any evidence of cancer disease, whereas DFS for all other patients was significantly (P = 0.022) lower (76.5 %)." (PMID 25005788, 2014). "We recently found evidence that STAT1 in esophageal squamous carcinoma (ESCC) cells exerts tumor suppressor function, and it regulates five key regulators of apoptosis or cell-cycle progression, including Bcl-2, Bcl-xL, survivin, cyclin D1 and p21." (PMID 25438156, 2014). "In bcl-2 positive patients, pathological stage and tumor location significantly affected prognosis, and pathological stage was an independent prognostic factor." (PMID 24555747, 2014).
tumor (continued). "Although inflammation is regarded as a possible initiator of cancer and COX-2 and Bcl-2 expression were reported to be tumor initiators or promoters, the malignant potential of CG should be examined in future studies." (PMID 24387269, 2014). "PNT2258 shows broad activity against a variety of tumor types with robust single-agent activity in DLBCL where BCL-2 transcription drives the genesis and survival of the tumors." (PMID 24832107, 2014). "The miR-34 family is composed of miR-34a,miR-34b and miR-34c and mediates tumour cell activities through cell cycle arrest, apoptosis or senescence, and metastasis 34–36, depending on its targets, such as the oncogenes BCL-2,c-MYC and c-MET8,10,35." (PMID 25213795, 2014). "Univariate analysis showed the highest DFS (87.9 %) for women having tumours with BCL-2 overexpression (class 2), while the lowest (64.9 %) for those with BCL-2-negative cancers (class 0)." (PMID 25005788, 2014). "This reinforces the importance of PCs in tumor cell survival, probably through activation/expression of various anti-apoptotic mediators such as BCL2." (PMID 24961901, 2014). "In recent years, several promising inhibitors of BCL2-proteins have been developed and thus the great challenge now is to explore how to best utilise these compounds in which tumour types." (PMID 26556430, 2014). "Real-time PCR array revealed a downregulated expression of the anti-apoptotic gene BCL2 in Spn4A-expressing tumor cells and an increased expression of the pro-apoptotic gene TNF." (PMID 24961901, 2014). "For example, up-regulation of caspase-8 inhibitors like Flice-like inhibitory protein or inhibition of caspase-8 by Bcl-2 can induce tumor resistance to chemotherapy drugs by decreasing cellular apoptosis." (PMID 25086656, 2014). "As an oncogene, Bcl-2 is also a direct target of miR-21 and plays an important role in the tumor cell apopposis pathway." (PMID 25084400, 2014). "Another structure-based synthesis has produced BM-957, a potent small-molecule inhibitor of Bcl-2 and Bcl-xL, which was capable of achieving complete tumor regression in a small lung cancer xenograft model." (PMID 25268519, 2014). "A common feature in many human tumors is overexpression of the pro-survival Bcl-2 family members Bcl-2 and Bcl-xL, which make tumor cells resistant to conventional cancer therapeutic agents." (PMID 25268519, 2014). "S1 can therefore interfere with the interactions of Bcl-2/Bax or Mcl-1/Bak, thus inducing apoptosis in various tumor cells, including liver and breast cancer." (PMID 25177684, 2014). "Given these multiple actions, the primary mechanism by which gossypol induces cell death in any particular tumor type is likely to vary, depending on the levels of anti-apoptotic BCL-2 proteins and other tumor cell-specific factors." (PMID 24824755, 2014). "The tumor cells were diffusely positive for S-100 protein, strongly positive for vimentin, and focally positive for BCL-2 and CD57." (PMID 25364450, 2014). "Matrine (active component of Sophora flavescence dry roots) in human gastric cancer MKN45 tumor cells activates caspase-3, 7 and up-regulates pro-apoptotic molecules Bok, Bak, Bax, Puma, Bim and induces apoptosis via Bcl-2." (PMID 25071577, 2014). "Tumor cells overexpress antiapoptotic proteins of the Bcl-2 (B-cell leukemia/lymphoma-2) family, which can lead to both escape from cell death and resistance to chemotherapeutic drugs." (PMID 25177684, 2014).
tumor (continued). "On the other hand, the TK/GCV system would induce downregulation of Bcl-2 and upregulation of caspase-9/-3 in the tumor cells, which increases the sensitivity to apoptosis induced by CTL." (PMID 25051201, 2014). "We focused our attention on docetaxel since: a) it represents the treatment of choice for CRPC; b) it has been shown to induce tumor cell death through upregulation of the proapoptotic protein Bax and downregulation of the antiapoptotic protein Bcl-2." (PMID 24722580, 2014). "We found a decrease in Bcl-2 and Bcl-xl protein, and an increase in Bax protein levels both in the tumour tissues of the mice and tumour cells treated with canstatin (P<0.05)." (PMID 27919040, 2014). "The levels of apoptosis-related proteins such as anti-apoptotic protein Bcl-2 and pro-apoptotic protein Bax were examined in total protein from tumor cells treated with DMSO or clotrimazole(40 μM) for 12 h, 24 h and 48 h." (PMID 24892421, 2014). "The expression of Bcl-2 in MM tumor tissue was significantly downregulated in mice treated with either TQ or bortezomib alone." (PMID 24504138, 2014). "On the other hand, it is well known that NF-кB is responsible for the activation of genes involved in proliferation and tumor survival, such as the apoptotic proteins Bcl-2 and Bcl-XL." (PMID 24495648, 2014). "Referring to Lauren's classification, we noted a distinct difference in the frequency of Bcl-2 expression depending on tumor differentiation." (PMID 24741635, 2014). "HDACI-mediated tumor cell apoptosis was restored by the overexpression of Bcl2, although G2-M phase arrest was unaltered." (PMID 24626188, 2014). "The expression of Bcl2 and its correlation with survival depends on various factors including host response, level of p 53 expression, tumor grade, and biological behavior of the tumor." (PMID 24864239, 2014). "Downregulation of anti-tumor (tumor suppressor) miR-125b in human cancers promotes survival, proliferation and invasion of tumor cells through de-repression of BCL2, BCL2L2, E2F3, ERBB2, FGFR2, MCL1, SIRT7, Smoothened and STAT3." (PMID 25364765, 2014). "It has also been demonstrated that miR-497 was downregulated and functioned as a tumor suppressor by targeting BCL2 in several cancers." (PMID 24520312, 2014). "We found that Bcl-2 expression significantly correlated with the depth of tumor invasion (p = 0.033)." (PMID 25438156, 2014). "Relation between expression of survivin and another antiapoptotic protein, Bcl-2, was found in different tumour tissues." (PMID 25140197, 2014). "We show that some GATA3 effects shift from tumor suppressing to tumor promoting during tumorigenesis, with deregulation of three genes, BCL2, DACH1, THSD4, representing major GATA3-controlled processes in cancer progression." (PMID 25410484, 2014). "To determine the expression of CAMK2N1, AR, pAKTser473, PSA, Bax, Bcl-2, p21, and Ki67 in tumor tissues, we conducted qRT-PCR and IHC staining in tumors." (PMID 25296973, 2014). "We noted that the phosphorylation of Bcl-2 was increased in the tumour tissues and cells treated with high concentration of canstatin (P<0.05)." (PMID 27919040, 2014).
tumor (continued). "Gos is a natural small molecule inhibitor for Bcl-2 or Bcl-XL that has been shown to act as a potent inducer of apoptosis in multiple tumor cell types." (PMID 25231749, 2014). "RV was shown to decrease tumor cell viability, an effect that can be reverted by overexpression of Bcl-2." (PMID 25126945, 2014). "Previous studies have confirmed that STAT3 alterations affect Bcl-2 and Bax protein expression (decreased Bcl-2 and increased Bax) and induce inflammation and apoptosis in many types of tumor cells." (PMID 25092271, 2014). "miR-16 can act as a tumor suppressor through pathways involving BCL2 and CCND1, validated targets (here also anti-correlated)." (PMID 23405235, 2013). "The activation of the p38 MAPK pathway and downregulation of a pro-survival protein (Bcl-2) significantly enhanced the anchorage-dependent tumor cell apoptosis in OSCC cells treated with tetrathiomolybdate." (PMID 24278362, 2013). "Bcl-2 has been found to function as a negative regulator of apoptosis and has been found to play an important role in tumor cell survival." (PMID 23675407, 2013). "EGFR has been shown to be associated with tumor proliferation and growth, Bcl-2 inhibits tumor apoptosis and MMP-9 and MMP-2 play an indispensable role in tumor invasion and metastasis." (PMID 23420470, 2013). "Using human ILBC cell lines, primary tumors and pre-invasive lesions as a model, the present study aimed to determine the relevance of the newly proposed relationship between E-cadherin and BCL2 for tumor development driven by CDH1 inactivation." (PMID 24023670, 2013). "Complexity of Bcl-2 and Bcl-xL functionality is reflected by a large number of studies that have been unable to reach consensus on their role in tumorigenesis and tumour-prognosis." (PMID 24050266, 2013). "KLF8 knockdown in the cancer cells resulted in reduced xenografted tumor growth in nude mice with decreased expression of cyclin D1 and Bcl-2, the upregulation of pro-apoptotic gene expression and apoptosis in the tumor cells." (PMID 23722127, 2013). "In this study, we found that BCL2 was consistently strong in the tumor cells in low-grade FLs, but was inconsistently medium to negative in grade 3 FLs." (PMID 24047469, 2013). "The expression of apoptosis regulatory caspase-3, Bax and Bcl2 was modulated in the BMC of orlistat-administered tumor-bearing mice." (PMID 24349275, 2013). "These cells were also strongly positive for BCL2, a transcriptional target of the NOTCH pathway, which characterizes developmental and tumor-associated neoangiogenic endothelium and is implicated in the cross-talk between endothelial and cancer cells." (PMID 23955600, 2013). "The expressions of PCNA, Ki-67, Bcl-2, Survivin, NS protein in tumor samples were significantly decreased in P + UTMD group, while those of Bax and Caspase-3 were up-regulated significantly." (PMID 23325045, 2013). "In an additional study, bcl-2 expression was compared with the expression of other markers in the primary tumor and lung metastases." (PMID 24137369, 2013). "Bcl-2 has previously been shown not only to inhibit apoptosis, but also to exert growth inhibitory activity on tumor cells, and to prevent their re-entry into the cell cycle from a G0-like state by distinct mechanisms." (PMID 23251241, 2013). "The significant increase in the Bax/Bcl2 index in DOX4/I2 + DOX4 suggests an enhanced DOX sensitivity that correlates with the marked reduction of tumor mass observed in this group." (PMID 23705792, 2013). "Positive expression of Survivin, PCNA, Ki-67, Caspase-3, Bcl-2, Bax or NS protein are those significant yellow or brown particles were observed within tumor cells." (PMID 23325045, 2013).
tumor (continued). "Various antibodies were used to assess Bcl-2 expression, and the cutoff in the number of positive cells defining a tumor with Bcl-2 overexpression varies from 5% to 50%, more than 10% for most studies." (PMID 24370277, 2013). "In combination with NVP-BEZ235 and CDDP, there was dramatic synergy in shrinking tumor volumes and inducing apoptosis through increasing Noxa, Bax and decreasing Mcl-1, Bcl-2." (PMID 23533654, 2013). "Immunohistochemistry revealed that tumor cells express Vimentin, Bcl-2, and Mic-2 with crisp cytoplasmic positivity suggesting the diagnosis as poorly differentiated small cell variant synovial sarcoma." (PMID 23762651, 2013). "After the slides consultation in our hospital, BCC was diagnosed as the tumor cells strongly expressed p63, Ki67, 34βE12 and bcl-2." (PMID 23941693, 2013). "For example, Tim-3 on ECs, by binding to a putative receptor on B16 tumor cells, resulting in NF-κB activation, Bcl-2 and Bcl-xL upregulation, and Bax downregulation, which finally leads to tumor cell resistance to apoptosis." (PMID 24339828, 2013). "BCL2 protein was expressed with consistent high intensity in the tumor cells in FL1 and FL2, but with inconsistent median to week intensity in FL3, and negatively in some large transformed cells in FL3." (PMID 24047469, 2013). "In the in vivo study, ATL-I effectively suppressed tumor growth (A549) in transplanted tumor nude mice with up-regulation of caspase-3, caspase-9, and Bax and down-regulation of Bcl-2 and Bcl-XL." (PMID 24172243, 2013). "Although they are typically regarded as having pro-tumor effects, expression of Bcl-2 and phosphorylated ERK1/2 in NSCLC patients receiving chemotherapy were positively correlated with recurrence-free survival." (PMID 23844053, 2013). "We have reported that tumor cell-derived VEGF induces Bcl-2 expression in endothelial cells, and that the Bcl-2 expression levels in tumor endothelial cells correlate directly with the rate of tumor growth." (PMID 24391922, 2013). "NF-κB regulated the expression of Mcl-1, Bcl-2, Bcl-XL, c-IAP1, c-IAP2, FLIP, and survivin, and their overexpression in numerous tumors has been linked to tumor cell survival, chemoresistance, and radioresistance." (PMID 24146961, 2013). "Further study demonstrated that the anti-tumor effect of PGPIPN is partially through promoting cell apoptosis by inhibiting BCL2 pathway." (PMID 23593287, 2013). "The ability of tumour cells to undergo apoptosis by chemotherapeutic agents is controlled by the ratio of Bax/Bcl-2 in the mitochondria." (PMID 23509778, 2013). "In the present study, 13 (37.1%) cases out of 35 showed Bcl-2 protein expression in tumor cells and 9 (25.7%) cases out of 35 exhibited high levels (>50.0% of tumor cells staining) of Bcl-2 protein expression." (PMID 24385807, 2013). "The Bcl2 proteins also represent a promising target for modulating tumor cell sensitivity to apoptosis." (PMID 23956872, 2013). "The proto-oncogene, bcl-2, is an inhibitor of apoptosis and its expression results in increased cell survival by rendering tumor cells resistant to apoptosis." (PMID 24137369, 2013).